NOTCH1 (notch receptor 1)
Diseases named in the same sentence as NOTCH1 in open-access papers (continued):
Sharing a sentence is not in itself a finding about the gene and the disease.
breast cancer (continued). "However, the expression of Notch 1 was enriched in the basal subtype of breast cancer (pooled OR = 2.53, 95%CI: 1.18–5.43, p = 0.009 and I2 = 74.3%)." (PMID 26121683, 2015). "Our meta-analysis suggests that Notch inhibitors may be useful in blocking the early progression of DCIS and that the outcomes of clinical trials for Notch1-targeting therapeutics could be improved by the molecular stratification of breast cancer patients." (PMID 26121683, 2015). "Here, we provide evidence for the Notch1–Slug signaling axis in breast cancer cells to promote EMT and further enhance the capacity of migration and invasion, which may improve our understanding of the regulatory networks governing EMT and cancer progression." (PMID 25645291, 2015). "Moreover, overexpression of Notch1 and/or its ligand Jagged1 is related to the poorest overall patient survival in human breast cancer." (PMID 25645291, 2015). "To investigate whether Notch1 mRNA abundance correlated with breast cancer survival, we analyzed published gene expression databases of breast cancer from Oncomine with survival information." (PMID 26121683, 2015). "The Notch1–Slug signaling axis may represent a potential therapeutic target for breast cancer therapy." (PMID 25645291, 2015). "In vitro experiments have revealed that Notch1 silencing reverses the EMT process and inhibits metastasis in breast cancer cells, which prompted us to investigate whether downregulation of Notch1 can regulate EMT in vivo." (PMID 25645291, 2015). "Precisely measuring the prognostic value of Notch1 may help to guide individual therapies for breast cancer patients." (PMID 26121683, 2015). "Notch1 was found in the majority of breast cancer tissues evaluated." (PMID 24716804, 2014). "Therefore, we assessed the possibility of SIRT1 and components of the Notch1 signaling pathway as prognostic biomarkers for breast cancer." (PMID 25420528, 2014). "Taken together, these findings suggested high SIRT1 may be breast cancer protective in a Notch1-depndent manner." (PMID 25420528, 2014). "Overexpression of active Notch1 enhances murine mammary tumor formation." (PMID 24970818, 2014). "To investigate whether the effect of visfatin on Notch1 upregulation was dependent on the breast cancer cell type, we knocked down visfatin and Notch1 in other breast cancer cell lines, including BT549, MCF-7, and T47D." (PMID 24970818, 2014). "However, relatively little is known about the upstream modulators and/or molecular mechanisms that regulate Notch1 expression in human breast cancer cells." (PMID 24970818, 2014). "Because NF-κB p65 mediated visfatin-induced Notch1 upregulation, we investigated whether a correlation between NF-κB p65 and Notch1 expression existed in human breast cancer tissues." (PMID 24970818, 2014). "SIRT1 expression and Notch1 signaling have been implicated in tumorigenesis in many cancers, but their association with survival in breast cancer has not been determined." (PMID 25420528, 2014). "To determine the possible mechanisms of sunitinib-induced the stemness of breast cancer stem cells, we used Western blot for examining whether sunitinib increases the expression of Notch1 in cultured MDA-MB-468 cells." (PMID 24914410, 2014). "Furthermore, we evaluated the prognostic value of SIRT1 and Notch1 signaling in patients with breast cancer." (PMID 25420528, 2014). "Majority of breast cancers were positive for Notch1, DLL4 and VEGF." (PMID 24716804, 2014). "We further examined whether NF-κB and Notch1 mediated the stimulatory effects of visfatin on breast cancer cells." (PMID 24970818, 2014). "The present study was undertaken to determine whether Notch1 signaling is affected by visfatin and to characterize the functional role of the visfatin-Notch1 axis in breast cancer." (PMID 24970818, 2014).
breast cancer (continued). "A recent study revealed that IL-6 activated Jagged1/Notch1 signaling contributes to bone metastasis of breast cancer, indicating that multiple pathways may be involved in the IL-6-mediated CSC regulation." (PMID 26932376, 2014). "Notch1 signaling has been proposed as a poor prognostic marker in breast carcinoma." (PMID 25420528, 2014). "In summary, our results confirm NOTCH1 as an EMT inducer in breast cancer cells, which may have implications in tumor growth, dissemination and metastasis." (PMID 23826634, 2013). "Recently, it has been reported that Notch-1 and Notch-4 could serve as prognostic markers in breast cancer." (PMID 22949821, 2012). "Recent studies suggest that deregulated NOTCH1 signaling may contribute to relapse and/or chemotherapeutic resistance in triple-negative basal-like breast cancers, and that NOTCH signaling may be required to maintain ER-negative tumors." (PMID 22992387, 2012). "Real-time quantitative PCR analysis revealed decreases in Hes1, Deltex1, and c-Myc expression levels in tumors isolated from dox-treated mice compared with untreated controls, thereby confirming repression of NOTCH1 signaling in the dox-treated mammary tumor-bearing mice." (PMID 22992387, 2012). "We then tested whether NOTCH1 activity was required for mammary tumor-initiating cell activity by using an in vitro tumorsphere assay." (PMID 22992387, 2012). "In addition, in breast cancer, NOTCH1 and NOTCH4 have been positively correlated with stemness, and blocking antibodies to NOTCH4 reduces mammosphere formation." (PMID 22225988, 2012). "In addition, accumulation of the cytoplasmic domain of Notch1 was apparent in many breast cancer cell lines and tumor tissues, indicative of active Notch1 signaling." (PMID 23342261, 2012). "In this study, we used three human breast cancer cell lines, MDA-MB-231, MCF-7, and SKBR-3, which expressed high levels of Notch-1, and we found that As2O3 elicited a significant effect on growth inhibition and induction of apoptotic cell death in breast cancer cells." (PMID 22949821, 2012). "Furthermore, breast cancer cells with Notch-1 siRNA treatment were more sensitive to As2O3-induced apoptosis." (PMID 22949821, 2012). "To determine whether NOTCH1 activity is required to maintain mammary tumor growth and survival in vivo, we administered doxycycline to tumor-bearing MMTV-tTA/TOP-ICN1 mice." (PMID 22992387, 2012). "We observed a 10-fold decrease in NANOG protein levels in the GSI-treated cells, suggesting that NANOG may be NOTCH1-regulated in mouse and human breast cancer cells." (PMID 22992387, 2012). "Breast cancer cells were transfected with Notch-1 cDNA or empty vector control (pcDNA3)." (PMID 22949821, 2012). "These relapsed mammary tumors may contain increased numbers of mammary tumor-initiating cells and/or harbor genetic changes that render the tumors NOTCH1 independent." (PMID 22992387, 2012). "We have identified Notch-1 as a novel target in trastuzumab-resistant breast cancer." (PMID 21847123, 2011). "Furthermore, Notch-1 mRNA was found to be elevated in breast cancer cells resistant to gefitinib, an EGFR TKI." (PMID 21847123, 2011). "In addition, Notch-1 has been recently suggested as a novel marker of trastuzumab resistance from human breast cancer tissue." (PMID 21847123, 2011). "Moreover, high ErbB-2 expression in tumour-initiating cells of ErbB-2-positive breast cancer cell lines coincides with high Notch-1 expression and activity." (PMID 21847123, 2011). "We have identified Notch-1 as a novel target in trastuzumab-resistant breast cancer in vitro." (PMID 21847123, 2011). "Notably, a recent study demonstrated reduced stem cell activity in response to Notch1 or Notch4 suppression using the same breast cancer cell lines described herein, which supports the use of gamma-secretase inhibitors in clinical trials." (PMID 21914219, 2011). "Furthermore, PEA3 is a transcriptional activator of both Notch-1 and Notch-4 in other breast cancer cells." (PMID 21679465, 2011).
breast cancer (continued). "Additionally, our results reveal a strong correlation between the expression of cleaved Notch1 and downstream targets in ~75% of cancers analyzed, indicating an aberrant activation of the Notch pathway in a vast majority of breast cancers." (PMID 20030805, 2009). "In order to see if the Notch-Ras/MAPK cooperation is involved in stem cell maintenance in breast cancers, we analyzed the activation status of the two pathways using antibodies against cleaved Notch1 and phosphorylated forms of Erk1/2, the downstream targets of the Ras-MAPK pathway." (PMID 20030805, 2009). "Alternatively, these drugs might block the signaling pathway of some as yet unidentified substrate(s) which antagonizes the effect of reduced Notch1 signaling on breast cancer cell survival and proliferation." (PMID 19660128, 2009). "In the present study, we used a combination of hierarchical clustering and overall survival analysis of a novel microarray dataset, meta-analysis of published gene profiling studies, and cell culture experiments to investigate a potential role of a Notch-1–survivin signaling axis in breast cancer." (PMID 19025652, 2008). "We next analyzed the expression of Notch-1 mRNA in an established breast cancer patient cohort." (PMID 19025652, 2008). "To determine whether a similar association occurs in vivo, we examined by immunohistochemistry a panel of basal breast cancer cases for expression of activated Notch-1 (NIC) and survivin." (PMID 19025652, 2008). "Consistent with the model presented above, recent studies have shown that survivin may function as a direct transcriptional target of Notch-1, thus controlling mitotic transition and resistance to apoptosis in breast cancer." (PMID 19025652, 2008). "This is consistent with the findings of studies on NOTCH1 in colorectal cancer, ovarian cancer, breast cancer, and hematological malignancies, indicating that upregulated expression of NOTCH1 may be one of the signals of poor prognosis across different types of cancers." (PMID 41306984, 2025). "CCL20-regulated PMN-MDSCs secrete large amounts of CXCL1 by binding to CXCR2 and activating the NOTCH1/HEY2 signaling pathway in BC cells, leading to an increase in breast cancer stem cells (BCSCs)." (PMID 38609997, 2024). "Thus, here we investigated the hypothesis that macrophage–cancer cell interactions induce MenaINV expression in breast cancer cells through cooperation between Notch1 and NF-κB signaling." (PMID 37024946, 2023). "Interestingly, Notch signaling in HER2- breast CTCs has been reported to mediate chemoresistance while, a contradicting study has signified the role of Notch1 in mediating CSC survival in HER2+ breast cancer, further pointing towards the complexity and pleotropicity of Notch signaling in cancer." (PMID 38269089, 2023). "Furthermore, NDR1 might function as a hub to modulate IL-6, TNF-α or Wnt3a induced activation of Notch1 signaling pathway and enrichment of breast cancer stem cells." (PMID 35508987, 2022). "Notch1 and ERK activation were associated with poor DFS and OS, and combinatorial targeting of the two pathways significantly reduced proliferation and survival in breast cancer cell lines, inhibited sphere formation, and yielded tumor regression in xenograft models." (PMID 36358725, 2022).
breast cancer (continued). "Investigations on the association of NOTCH1 rs3124591, NOTCH3 rs1043994, and NOTCH4 rs3830041 with the risk of human cancers are rare, however, several studies have shown a link between NOTCH2 related rs11249433 and increased risk of breast cancer especially in women of European ancestry." (PMID 34257585, 2021). "The Notch signaling system that contains four Notch receptors (Notch1- Notch4) and five canonical ligands (Dll1, Dll3, Dll4, Jagged1 and Jagged2), plays important roles including carcinogenesis, cancer stem cell renewal, angiogenesis, and chemotherapy resistance in the progression of breast cancer." (PMID 33413403, 2021). "Indeed miR-34a may affect positively in the modulation of drug sensitivity in breast cancer by suppression of NOTCH1, BCL-2, and CCND1." (PMID 33773546, 2021). "Additionally, Notch1-IC aberrant overexpression correlates with leukaemia and breast cancer." (PMID 31605148, 2020). "Therefore, Psoralidin may prevent the incidence and metastasis of breast cancer by significantly inhibiting Notch-1 in breast cancer cells." (PMID 33344242, 2020). "However, as reported in the previous studies, S473 phosphorylation on AKT automatically increased in NICD activated cells at the 72th h after transfection, and suppression of Notch1 downregulated AKT phosphorylation/activation in breast cancer cells at 48th h after transfection." (PMID 31057403, 2019). "ERα expression levels were higher in the basal layer of prostate cancer, whilst expression was observed in the luminal layer of breast cancer, suggesting that the mechanisms of E2 regulating Notch1 in PCa may be tissue type dependent, a point that warrants further investigation." (PMID 31122254, 2019). "Therefore, VPA may be used in the combined therapy with CDDP against a very aggressive type of breast cancer—TNBC with increased Notch1 activity." (PMID 31357442, 2019). "Together with our data in luminal breast cancer cells and the observations of the Espinosa group, these observations suggest that IKKα mediates Notch1 nuclear effects in multiple cancer cell types, and may be a key, druggable mediator downstream of Notch in cancers where Notch1 is activated." (PMID 30564555, 2018). "Additionally, breast cancer patients with Notch-1 positive had shorter disease-free survival, indicating that Notch-1 may be involved in metastasis and is closely correlated with breast cancer stem cells." (PMID 28977931, 2017). "Moreover, NOTCH1 inhibition prevented EZH2-mediated CSC expansion in breast cancer." (PMID 28415635, 2017). "Therefore, dual targeting of both the CCR7 receptor and Notch1 signaling axes may be a potential therapeutic avenue to specifically inhibit the functions of breast cancer stem cells." (PMID 28137279, 2017). "Therefore, further study of the mechanisms of Notch1 signaling in breast cancer progression, as we show here, might lead to the identification of novel therapeutic targets within the Notch1 signaling cascade that might be better tolerated in patients." (PMID 27901093, 2016). "Further stratification of patient groups based on inverse Notch1/NUMB expression improved the predictive capability of NUMB for DDFS (p = 0.0004) in breast cancer patients (right), suggesting that NUMB may be another significant predictor of distant metastasis." (PMID 27506933, 2016). "Interestingly, extrusion of Notch1 as full receptor and extracellular portion could be also observed in the supernatant of human breast cancer cells." (PMID 27364742, 2016). "Then, we examined whether Notch1 had a pivotal role in regulating Slug expression in breast cancer." (PMID 25645291, 2015). "However, the prognostic value of Notch1 for breast cancer has yet to be confirmed." (PMID 26121683, 2015). "The Notch1–Slug axis might play an important role in breast cancer progression." (PMID 25645291, 2015).
breast cancer (continued). "In addition, elevated expression of Notch1 in human breast tumors correlates with poor overall patient survival, whereas Notch1 overexpression or depletion affects the proliferation, migration, and invasion of breast cancer cells." (PMID 24970818, 2014). "In this report, of four breast cancer cell lines studied, visfatin regulated Notch1 expression only in the MDA-MB-231 and BT-549 cell lines, which are TNBC cell lines, suggesting that targeting the visfatin-Notch1 axis may be an efficient strategy to improve the survival rate of TNBC patients." (PMID 24970818, 2014). "Thus, Notch1 could be a prognostic biomarker for the pathogenesis of breast cancer; as such, it may represent a novel therapeutic target." (PMID 24970818, 2014). "Study of the visfatin-Notch1 axis may offer new therapeutic directions for breast cancer." (PMID 24970818, 2014). "Since the discovery of Notch1 gene alterations in T-cell acute lymphoblastic leukemia/lymphoma, deregulated Notch signaling has been connected to many solid tumor pathologies and different cancer types (leukemia, neuroblastomas, skin, cervical, lung, prostate, and breast cancer)." (PMID 25717438, 2014). "However, despite increasing interest in SIRT1 and Notch1 signaling, their expression patterns and prognostic significance in breast carcinoma are unknown." (PMID 25420528, 2014). "Notch activation has been shown to induce an epithelial to mesenchymal transition in breast cancer Given that Notch1 expression was associated with ICC metastasis, we further investigated whether a link exists between Notch1 expression and the EMT phenomenon in ICC." (PMID 23688168, 2013). "In addition, no NICD1 staining was seen in sections of the MCL cell line MAVER-1, which has wild type NOTCH1 alleles and is devoid of NICD1, or in the breast cancer cell line HCC1587, which has wild type NOTCH1 alleles and instead has an activating deletion involving NOTCH2." (PMID 23825651, 2013). "In addition to a small subset of breast cancers and (as expected) more than half of T-LLs, our screen of human cancers indicates that NOTCH1 activation is prevalent in CLL and also occurs in a subset of peripheral T cell lymphomas and a high fraction of angiosarcomas." (PMID 23825651, 2013). "Importantly, the ability of these cells to form tumorspheres in vitro remains dependent on the expression of intracellular NOTCH1, as treatment of primary mammary tumor cells with doxycycline results in a >75% decrease in the number of tumorspheres (P < 0.0001)." (PMID 22992387, 2012). "Although CSL sites are present in the mouse Nanog regulatory region, we were unable to demonstrate NOTCH1 or Mastermind-like 1 recruitment to the mouse Nanog locus, leading us to speculate that NOTCH1 may indirectly regulate Nanog expression in mammary tumor- initiating cells." (PMID 22992387, 2012). "To determine whether NOTCH1 contributes to the regulation of NANOG in human breast cancer cells, we treated the basal-like human breast cancer cell line MDA-MB-231 with the γ-secretase inhibitor (GSI) Compound E to interfere with NOTCH1 processing and assayed NANOG expression levels." (PMID 22992387, 2012). "Thus we hypothesized that targeting of the PEA3 and/or Notch pathways might provide a new therapeutic strategy for triple-negative breast cancer as well as possibly other breast cancer subtypes where PEA3 regulates Notch-1 and/or Notch-4." (PMID 21679465, 2011). "We have shown for the first time, to our knowledge, that PEA3 is a novel activator of Notch-1 and Notch-4 transcription in different subtypes of breast cancer cells and could prove to be an important therapeutic target, possibly upstream of Notch-1 and/or Notch-4 signaling." (PMID 21679465, 2011). "Finally in Notch1-induced mammary tumors it was shown that ablation of c-Myc reduces tumor incidence and increases tumor latency, suggesting that Myc might be an attractive target in cancers with deregulated Notch signaling." (PMID 19785743, 2009).